BCL2 (BCL2 apoptosis regulator)
Diseases named in the same sentence as BCL2 in open-access papers (continued):
Sharing a sentence is not in itself a finding about the gene and the disease.
tumor (continued). "BCL2 overexpression in a wide range of human tumours made G-quadruplex structures within its gene promoter attractive targets for cancer therapeutics." (PMID 33638996, 2021). "More importantly, they were able to reduce the anti-apoptotic Bcl-2 protein level, inhibiting tumor growth in a mouse xenograft tumor model after an intratumoral injection." (PMID 34065544, 2021). "The development of various BCL-2 inhibitors as the tumor cells’ apoptosis regulators is evolving as a single drug or administered with other therapeutic agents." (PMID 34575429, 2021). "Since we planned to analyzed Bcl-2 and miR-383 levels in GC versus paired non-tumor tissue (NT), we first excluded the effects of intra-tumoral inflammatory cells on analysis of total tumor tissue." (PMID 33402109, 2021). "Many kinds of tumors exhibit overexpression of anti-apoptotic proteins (Mcl-1, Bcl-xL, and Bcl-2), near all anti-tumor drugs targeting the Bcl-2 family have focused on the inhibition of Bcl-xL and Bcl-2." (PMID 34811352, 2021). "This study showed that the coculturing of tumor cells with Bcl-2-expressing EC conferred anoikis resistance on the tumor cells via the activation of E-selectin-FAK signaling." (PMID 33854965, 2021). "The tumor compartment of primary samples had significantly higher expression of immune cell markers CD45, CD8, ARG1, GZMB, BIM, BCL2, showing brain metastases have very few immune cells infiltrating in the tumor epithelium." (PMID 34838031, 2021). "Some investigations have revealed that a miR-197-mediated CKS1B/STAT3 axis exerts a role in tumor progression, which is regulated by different genes, such as Bcl-2, c-Myc, and cyclin D125." (PMID 34907223, 2021). "In the endoplasmic reticulum, it is known to interact with and suppress the anti-apoptotic functions of Bcl2 and BclXL,89 suggesting a role as a tumour suppressor." (PMID 33927352, 2021). "Treatment of the compound inhibited wound healing and migration of tumor cells, while proteins like Bcl-2, Bax, and caspase 3 were also altered." (PMID 37304673, 2021). "MiR-34a acts as a tumor suppressor miR by down-regulating its target genes such as BCL-2 and SIRT1 and Notch1, Wnt/β-catenin signaling pathway, fra-1 and MYC." (PMID 34199293, 2021). "Second, it also demonstrates that KLF5 downregulation inhibits tumor growth by increasing apoptosis, as revealed by the downregulation of anti-apoptotic factors, bcl-2 and bcl-xL as well as cleavage of PARP and caspase-3 in both PTC cell lines." (PMID 33430300, 2021). "In this regard, it has been demonstrated that both Bcl-2 and Bcl-XL can also act as crucial regulators of other important cellular processes, such as proliferation, autophagy, tumor progression, DNA repair, and angiogenesis." (PMID 34299603, 2021). "Altered expression of apoptosis-related proteins Bcl-2, Bax and Caspase-3 in vitro and in vivo confirmed that the tumour suppression effect of LMTK-3 was mediated by modulating cell apoptosis." (PMID 34064250, 2021). "According to the Revised Fourth Edition of the WHO Classification of Tumours of Haematopoietic and Lymphoid Tissues, at least 50% and 40% of neoplastic cells should express BCL2 and MYC, respectively, in order to consider a DLBCL-NOS patient as a DE." (PMID 33803671, 2021). "Bcl-2 is a key regulator of mitochondrial outer membrane permeability, which takes part in tumor cell apoptosis by regulating cyt-C release and Caspase activation." (PMID 35116035, 2021). "The levels of miR-383 were lower while the levels of Bcl-2 levels were higher in GC specimens, compared to tissue from the adjacent non-tumor region." (PMID 33402109, 2021).
tumor (continued). "Compared to those in OSE controls, ZEB2, N-cad and Bax were higher in HGSOC tumour tissues, while E-cad and Bcl2 were lower, and these changes were amplified with progressing stage." (PMID 34211089, 2021). "The expression levels of MMP2, MMP9, Bax, Bcl-2, and caspase-3 in the tumor organizations were detected with Western blot." (PMID 33391431, 2021). "Anti-apoptotic Bcl-2 proteins play a major role in the progression of various neoplasms and fuel rapid cell cycle regulation, angiogenesis, and regulation of gene expression." (PMID 34638779, 2021). "Gambogic acid and gallic acid can upregulate the Bax protein expression and downregulate the Bcl-2 protein expression, inducing tumor cell apoptosis." (PMID 34675987, 2021). "Several studies have demonstrated that Bcl-2 plays important anti-apoptosis roles in various cell types, including tumor cells, and Bcl-2 inhibition is a critical area of anti-cancer drug development." (PMID 33429845, 2021). "Accumulating evidence indicates that the high expression of Bcl-2 pro-survival protein positively correlates with the drug resistance;2 however, the effect of Bcl-2 siRNA on intrinsic tumor resistance to metallodrugs is rarely reported." (PMID 34163720, 2021). "Consistently, high expression of BCL2 was found in tumor tissues of CRC patients in contrast to normal tissues." (PMID 33838016, 2021). "Tumor cell apoptosis is regulated by interaction of numerous tumor suppressor genes and oncogenes, such as Bcl-2 and Bax." (PMID 34249261, 2021). "For apoptosis pathway analysis, the upregulated expression of bax expression was detected, while the expression of bcl-2 was decreased in the iturin A-treated tumor tissue." (PMID 33970365, 2021). "In the present study, we have also found that DNA methylation, which affects the levels of IGFBP2 expression, also unbalances BCL2 expression in two different tumor cell line models (HEK293T and MCF7)." (PMID 34434494, 2021). "GPR109a binding exerts a tumor suppressive effect through reduced expression of Bcl-2 and Bcl-xL, as well as through regulation of the Wnt/β-catenin signaling pathway that is fundamental to colorectal carcinogenesis." (PMID 34359944, 2021). "To date, several studies have shown that the Hh pathway is able to inhibit cell death via upregulating the anti-apoptotic gene Bcl2 in human tumor cells, providing Hh pathway inhibitors as proapoptotic drugs for tumor treatment." (PMID 34561426, 2021). "The tumor microenvironment exerts a protective role that withholds the levels of Bcl-2-induced cell death." (PMID 34381700, 2021). "Several anti-apoptotic proteins, such as Survivin and members of the Bcl family (Bcl-XL, Bcl-2, and Mcl-1), which are essential for tumor cell survival, are direct target genes of STAT3 and downregulated as a consequence of STAT3 inhibition." (PMID 34638708, 2021). "This metabolic shut down increases the activation of the anti-apoptotic BCL2 protein, promoting tumor growth and progression, likely by reducing mtROS." (PMID 34065551, 2021). "Bcl-2-related tumor resistance to anticancer drugs can be overcome by silencing the cellular Bcl-2 gene via RNA interference." (PMID 34163720, 2021). "CUR significantly changed the mRNA expression of BCL2 and CASP3 in B16-F10 tumor cells in comparison to untreated control cells (BCL2 (P = 0.039) and CASP3 (P = 0.031))." (PMID 34825002, 2021). "Bcl-2 as an anti-apoptotic protein has been shown to enhance cell survival by inhibiting apoptosis and enhance the sensitivity of tumor cells to chemotherapy drugs." (PMID 33546294, 2021). "Treatment of tumor cells with MJ (2.5 mM) for 18 h resulted in a significant decline in the expression of Bcl-2 compared to control." (PMID 33716751, 2021).
tumor (continued). "The activation of Bcl-2 has been shown to enhance tumor growth, invasion, motility, tumor spreading, metastasis, and inhibition of apoptosis." (PMID 34181356, 2021). "It has been reported that STAT3 inhibition induces tumor cell death and increases apoptosis of tumor cells by increasing the Bax/Bcl-2 ratio." (PMID 33807148, 2021). "Analysis of the Bax, Bcl-2, E-cad, N-cad, and Snail expressions in tumor tissues by IHC staining showed that CircRNA_2646 overexpression lowered Bax and E-cad levels, but enhanced the Bcl-2, N-cad, and Snail levels in ESCC tissues of mice." (PMID 33976115, 2021). "Loss of another miRNA, miR-34, has been detected in CD44 + /CD133 + tumorsphere-forming and tumor-initiating PCSCs, accompanied with increased levels of Notch/Bcl-2." (PMID 34453639, 2021). "The results showed that AGE up-regulated the pro-apoptotic Bax protein expression and down-regulated the anti-apoptotic Bcl-2 protein expression, which tends to tumor growth suppression and sensitizes CRC cells to death." (PMID 34202548, 2021). "The authors demonstrated that Bcl-2 can be pharmacologically targeted with a peptide that mimics Nur77, preferentially inducing apoptosis in Bcl-2 overexpressing paclitaxel-resistant cells and inhibiting tumor growth in a zebrafish xenograft model." (PMID 33525637, 2021). "Up-regulation of miR-15a/16-1, regulated by CXCR4, results in the repression of BCL-2 and cyclin D1. miR-15a/16-1 increases apoptosis and reduces the proliferation and survival of tumor cells." (PMID 33718173, 2021). "TCS treatment inhibited tumor proliferation by downregulating Ki67 and Bcl2 protein expression while accelerating tumor apoptosis." (PMID 33750370, 2021). "It will be interesting to design solid-tumor-targeting CAR-T cells with Bcl-2 overexpression and to test their anti-tumor efficacy in solid tumor models in future investigations." (PMID 33429845, 2021). "The anticancer effect of ATO is mainly through upregulating the apoptosis promoter gene BAX and downregulating the apoptosis inhibitor gene BCL-2 to induce tumor cell apoptosis." (PMID 34458205, 2021). "Since little is known about the expression pattern of SOX2 and apoptotic genes in HCC, we aimed to determine the prognostic significance of SOX2, Bax, and Bcl-2 in clinicopathological features, tumor progression, and survival rate of the HCC patients." (PMID 34436030, 2021). "In vivo experiments further showed that MIC-1 markedly inhibited the growth of xenograft tumors in mice, and greatly increased Bax/Bcl-2 ratio in tumor tissues." (PMID 35059399, 2021). "The treatment of the K562 cells by the anti-tumor drug nilotinib resulted in a decrease of Bcl-2 (inhibitor of apoptosis) and an increase of Bax concentrations (which promotes apoptosis)." (PMID 34073054, 2021). "To further confirm the role of β-catenin and BCL2 in gastric resistance development, we examined the expression of β-catenin and BCL2 in tumor tissues from patients." (PMID 34319913, 2021). "BCL2 overexpression inhibits apoptotic cell death and activates cellular proliferation and tumor progression." (PMID 34099764, 2021). "While encouraging anti-tumour activity in clinical trials has led to the approval of the Bcl-2 inhibitor, venetoclax, the therapeutic utility of dual Bcl-2/Bcl-xL inhibitors such as navitoclax has been limited by accompanying toxicities." (PMID 33495510, 2021). "HCL cells express B cell lymphoma 2 (Bcl-2), an anti-apoptotic protein that plays a central role in evading programed cell death, promoting tumor growth and disease progression in cancer." (PMID 34381700, 2021). "In a range of hematological and solid cancers, MCL-1 has been implicated in tumor formation, cell survival, and treatment resistance, including resistance to BCL-XL and BCL-2 targeting." (PMID 35008216, 2021). "Bcl-2 expression exhibited an opposing trend because tumor cells become dependent on anti-apoptotic Bcl-2 to survive." (PMID 33925400, 2021).
tumor (continued). "Some miRNAs display tumor suppressor effects, such as miR-29b, which inhibited the expression of antiapoptotic genes Mcl-1 and Bcl-2, and promoted spontaneous apoptosis of tumor cells." (PMID 34084160, 2021). "The expression of Bcl-2 and Bcl-6 in the transplant group was notably downregulated compared to control tumor." (PMID 33505491, 2021). "In tumour cells, upregulation of anti-apoptotic Bcl-2 proteins, such as Bcl-2, Bcl-xL, Mcl-1 and Bcl-w prevent apoptosis and can lead to chemo-resistance." (PMID 33495510, 2021). "Subsequent studies demonstrated that their tumor suppressor function was, at least in part, through the activation of cell apoptosis by targeting BCL2, MCL1, and CDK6." (PMID 34944752, 2021). "In line with changes in SOX2 expression, higher expression levels of Bcl-2 were also coordinated with tumor grade (p = 0.003) and the progression of the tumor (p = 0.04)." (PMID 34436030, 2021). "(S-nitrosylation of BCL-2 at Cys158 and Cys229 was found to be a major mechanism to suppress apoptosis of tumor cells under stress)." (PMID 33925645, 2021). "miR-21 promotes cell proliferation and inhibits apoptosis by suppressing tumor suppressor genes, including Bcl-2." (PMID 33741523, 2021). "IL-6 signaling induces and activates STAT3, supporting cancer cell survival and proliferation by upregulating expression of the anti-apoptotic protein, Bcl-2, in various tumor cell lines, such as melanoma cells." (PMID 33917793, 2021). "It was also reported that parenteral administration of nanoliposomes-Bcl-2 siRNA on MDA-MB-231 tumours in an orthotopic xenograft model in mice significantly reduced tumour growth." (PMID 34575883, 2021). "The percentage of Ki67+ tumor cells was reduced in the majority of cases where BCL-2 was upregulated in response to lapatinib." (PMID 33951110, 2021). "Findings were confirmed using an external HGSC database, GSE26712 (Siamakpour-Reihani), showing that women with high bcl-2 tumor expression had significantly worse survival (p = 0.002) and approximately 2-fold higher risk of death." (PMID 33815656, 2021). "This can result in enhanced Bcl-2 transcription and suppression of apoptosis, which promotes tumor development and progression." (PMID 33613749, 2021). "ISL regulated the expression of Bcl-2, the mTOR pathway, and the expression of other related proteins, triggering apoptosis and autophagy in drug-resistant tumor cells, while the inhibition of autophagy enhanced ISL-mediated drug-resistant cell death." (PMID 33494431, 2021). "MiR-15a-5p is a tumor suppressor, promoting apoptosis and inhibiting cell proliferation by targeting multiple oncogenes, including Bcl-2, Mcl1, CcnD1, and Wnt3A33,34." (PMID 33456354, 2021). "Increase of Bax/Bcl-2 ratio and decrease of Ki67 protein expression; decrease of blood concentrations of tumor growth factors and tumor concentrations of VEGF and EGF expressions." (PMID 34630112, 2021). "Apoptosis of a tumor cell which is locked in the G1 (static) phase can be additively primed by concurrent inhibition of BCL2." (PMID 33530335, 2021). "In MCF-7-xenograft tumour nude mice and immunosuppressive mice, 30 mg/kg Phy treatment inhibited tumour growth from the 8th day, and reduced Bcl-2 and Bcl-xL >50%, HO-1 and SOD-1 > 70% in tumour tissues of immunosuppressive mice." (PMID 33715588, 2021). "Bcl-2, Bcl-xL overexpression reduce apoptosis and facilitate immortalization of damaged cells, resulting in excessive proliferation and tumour development." (PMID 34174900, 2021). "Immunohistochemical analysis of bax, bcl-2, caspase-3 and Ki 67 were examined from distant tumor tissues." (PMID 34993150, 2021).
tumor (continued). "Phenotypically, the spleen and tumor-derived donors expressed similar levels of Bcl-2, TIM3, CXCR3, PD-1, and had undergone similar patterns for memory vs effector differentiation as determined by CD62L, CD127, and KLRG-1." (PMID 34867942, 2021). "The combination treatment between doxorubicin and nanoliposomes-Bcl-2 siRNA enhanced the tumour efficacy in TNBC in vivo model." (PMID 34575883, 2021). "In tumour tissues of Phy-treated nude mice, Phy sharply enhanced the expression levels of cleaved-caspase-3 and Bax, and suppressed the expression levels of Bcl-2 and Bcl-xL." (PMID 33715588, 2021). "Bcl-2-like protein 11 (BCL2L11 or BIM) belongs to the B-cell lymphoma-2 (BCL-2) family proteins that play key roles in regulating apoptosis of tumor cells." (PMID 34722761, 2021). "Increased expression of Ccl5 promotes tumour proliferation and metastasis, high expression of Bcl2 inhibits apoptotic death, favouring neoplastic cells proliferation and Gstp1 is a marker of preneoplastic foci in liver tissue." (PMID 34650394, 2021). "This causes, in the downregulation of antiapoptotic protein, BCL-2, and cleavage of MCL-1 suppressing tumor growth." (PMID 33804548, 2021). "Treatment with RSV acted similarly on FaDu tumor cells (p < 0.005, **) and HaCaT cells (p < 0.006, **), and it resulted in the inhibition of BCL-2 gene expression compared to untreated cells." (PMID 34204834, 2021). "Studies have reported that Bcl-2 is highly expressed in several cancers and can protect tumor cells from apoptosis by inhibiting the adapters required for activation of the caspases that dismantle the cells." (PMID 34170850, 2021). "Bcl-2, which affects apoptosis and drug resistance, was regulated in 13 compounds, and Bax, a pro-apoptotic molecule that also functions as a tumor suppressor, was regulated in 10 compounds." (PMID 33466408, 2021). "Fostering the intrinsic way of apoptosis with BH3 mimetics is one approach to overcome resistant tumor cells as these agents antagonize the pro-survival Bcl-2 proteins, thus inducing cell death." (PMID 33523262, 2021). "The key point to suppress tumor growth is to find an inhibitor of BCL2 to restrict its activity so as to resist tumor growth." (PMID 34259934, 2021). "TSLP is a critical tumor survival factor required for metastasis and it promotes survival through induction of Bcl-2 expression." (PMID 33430381, 2021). "Bcl-2 inhibits these pro-apoptotic proteins efficiently, but the Bcl-2 activation during chemotherapy in different tumor cells applies different mechanisms." (PMID 33402109, 2021). "Consistently, there were also significantly decreased BCL2 expression level in WHSC1-knockdown xenografted tumor tissue compared with control xenografted tumor as assessed by immunohistochemistry and Western blot." (PMID 33469000, 2021). "CTND was co-loaded with Bcl-2 siRNA in tumor-targeted nanoparticles (NPs) to achieve a synergistic effect." (PMID 34163720, 2021). "On the other hand, a combination (TZB+ATV) therapy can increase the anti-tumor efficacy by decreasing the overall expression levels of IL-6, NFκB (green dashed), and Bcl-2 (red solid), and by increasing the overall BAX levels (blue circle)." (PMID 34669701, 2021). "Evading apoptosis by upregulation of BCL2 contributes to tumor initiation and maintenance, thereby targeting BCL2 is currently becoming an attractive therapeutic approach for the treatment of various malignant disorders." (PMID 33777762, 2021). "Docetaxel suppresses tumor growth by various mechanisms such as inhibiting microtubule depolymerization, interfering with the expression of apoptotic genes (bcl-2 and bcl-xL), suppressing tumor angiogenesis, and/or inhibiting cellular signaling pathways." (PMID 33925581, 2021).